KRT18 (keratin 18)
Diseases named in the same sentence as KRT18 in open-access papers (continued):
Sharing a sentence is not in itself a finding about the gene and the disease.
tumor (continued). "Snail is known to downregulate the expression of E-cadherin and cytokeratin 18 and to upregulate the expression of vimentin and thus its expression leads to a mesenchymal phenotype of the tumor cells while the cohesion of the cells at the same time decreases." (PMID 23157169, 2012). "This was accompanied by an increased expression of E-cadherin and Keratin-18 and a decreased expression of vimentin in tumor tissues." (PMID 20573255, 2010). "We also evaluated plasma levels of caspase-cleaved cytokeratin-18 (CK-18) as a surrogate marker of tumour apoptosis." (PMID 20733579, 2010). "Both prostate specific genes (e.g., PSA/Kallikrein 3 and Kallikrein 2) and epithelial marker genes (e.g., keratin 18 and desmoplakin) were expressed in tumor epithelial cells." (PMID 20426842, 2010). "To molecularly determine if these tumours reverted to a more epithelial phenotype, we stained for the epithelial marker cytokeratin 18 and the mesenchymal marker vimentin." (PMID 17406365, 2007). "In one study, caspase-cleaved cytokeratin 18 (CK18-Asp396) serum marker was used to assess tumor apoptosis in vivo." (PMID 19662190, 2007). "M30-ApoptosenseTM plasma Elisa detects a caspase-cleaved fragment of cytokeratin 18 (CK18), believed to be a surrogate marker for tumour cell apoptosis." (PMID 15685240, 2005). "In this study, we investigated the transcriptomic and spatial characteristics of hybrid circulating tumor cell (CTC)-like cells co-expressing epithelial (KRT18) and immune (CD45/PTPRC) markers, termed KP_Pos, to elucidate their origin and clinical significance." (PMID 41355965, 2026). "Previous studies have reported that overexpression of KRT18 may lead to adverse effects, including tumor-like cellular behavior." (PMID 40458763, 2025). "Indeed, TD-PCLS maintain tumor structure in ex vivo culture environment, as shown by cytokeratin 18–positive (CK18-positive) cells, which are structurally present in the TD-PCLS as in the tumor tissue." (PMID 40728884, 2025). "KRT19, an intermediate filament protein, contributes to cytoskeletal organization and epithelial integrity in luminal subtypes (e.g., MCF7 and T47D) and is associated with cell adhesion and tumor progression via interactions with KRT8, KRT18, and EPCAM, as suggested by STRING analysis." (PMID 40806403, 2025). "The miR-18a/low tumours had higher expression of the luminality-associated genes like ESR1, GATA3, FOXA1, XBP1 and TFF1 and a lower expression of the basality-associated genes such as KRT18, KRT17, FOXC1, ANLN, STIL and MIA (p < 0.05)." (PMID 38786043, 2024). "KRT18 had four variants found in all samples, though none satisfied the oncogenic (or “Driver” predicted as tumor driver according to Cancer Genome Interpreter) threshold." (PMID 37627102, 2023). "Obviously, the cadherin binding related genes including CTNNB1, CDH1, ITGA6, KRT18, and PROM1 were significantly associated with EpCAM, which also implied that EpCAM could play a role in tumor metastasis." (PMID 35517503, 2022). "Proteolytic activities have been previously proposed to generate new tumor biomarkers, for example in the form of patterns of the serum peptidome amplified by the proteolytic activities of tumor-derived proteases or by the proteolytic degradation of cytokeratin-18 by caspases during apoptosis." (PMID 36010852, 2022). "Furthermore, mesenchymal cells such as fibroblastic reticulum cells (CK‐positive interstitial reticulum cells, CIRCs) can also express KRT18 in reactive LNs and occur in large numbers in tumor‐draining LNs that are subcapsular in the paracortical regions." (PMID 34719102, 2022). "KRT8 and KRT18 were commonly expressed in the three tumor cell subtypes." (PMID 35494058, 2022). "Using M30 antibodies, which specifically bind caspase-cleaved cytokeratin-18 and thus mark epithelial and tumour cell apoptosis, we could furthermore detect M30-positive apoptotic tumour cells in CRC pseudolumina." (PMID 35121727, 2022).
tumor (continued). "KRT18 showed a significantly higher expression level in tumor tissues compared to normal tissues." (PMID 34290732, 2021). "Cell cycle analysis was subsequently performed with the Krt18+ tumor cells." (PMID 34373258, 2021). "Considering that tumor tissue is complicated in cell type and deregulated genes, these KRT18-dependent RASEs could be regulated by other factors." (PMID 34290732, 2021). "Interestingly, the plasma levels of biomarkers M30 and M65 (cleaved and full-length cytokeratin 18) correlated significantly with the tumor load of the patients (r = 0.55, p < 0.001 and r = 0.42, p = 0.002)." (PMID 32290637, 2020). "Only the apoptosis markers M65 and M30 (full-length and cleaved cytokeratin 18) correlated with tumor load and might be useful markers for diagnosis, which confirms published data." (PMID 32290637, 2020). "Furthermore, oral administration of xanthohumol decreased tumor volume and weight in patient-derived xenografts (PDXs) tumors having overexpressed KRT18." (PMID 32509787, 2020). "Importantly, our own immunohistochemical staining of bone biopsy tissues from metastatic patients confirmed high HO-1 presence in the cytokeratin 18-positive (CK18+) tumor cells colonizing the bone marrow." (PMID 29311669, 2018). "Furthermore, pitavastatin increased the secretion in two cell lines of caspase-cleaved cytokeratin 18 (ccCK18), a potential biomarker of tumour cell apoptosis in cancer patients." (PMID 28710496, 2017). "Thus, our results suggest that OC inhibits tumor metastasis partially by increasing the keratin 18 and tubulin levels." (PMID 25973684, 2015). "Marked increase in cleaved cytokeratin 18 levels was also observed in the control tumor lysate." (PMID 26234505, 2015). "Increased staining of keratin 18 in the lung tissue from OC-treated mice was o8bserved compared with the control mice, suggesting that OC may increase keratin 18 in the mice tumor model." (PMID 25973684, 2015). "Measurement of caspase-cleaved (CK18–Asp396) or total cytokeratin 18 (CK18) from epithelial-derived tumours could be a simple, non-invasive way to monitor or predict responses to treatment." (PMID 19603019, 2009). "KRT18 could be an important tumor marker for clinical diagnosis of CRCs." (PMID 33898197, 2021). "Tumor cells were identified using EPCAM, KRT18, and AFP as markers, while T/NK cells were identified by using the markers CD3D, CD3E, and GZMA." (PMID 40740783, 2025). "Our analysis focused on tumor cells contained in the TD-PCLS and epithelial cells in healthy PCLS, asking for the capability not only proliferate (positive for EdU and CK18; cytokeratin 18), but also to undergo apoptosis (positive Tunel and CK18)." (PMID 40728884, 2025). "Immunocytochemical analysis of all DEN treated groups was carried out for tumor markers (collagen IV, PCNA, keratin 18 and E-Cadherin)." (PMID 40475465, 2025). "All PDGCAs expressed markers of tumor epithelial and stem cells (EPCAM, CDH1, KRT18, CA9, CD24, CD133), stromal and extracellular matrix components (COL3A1, COL5A1, DCN, PDGFRA, and PDGFRB), and mesenchymal stem cells (CD73, CD105, CD90)." (PMID 40723172, 2025). "In a similar approach, we identified the cell cluster of ADC and confirmed the tumor cells cluster based on the expression of EPCAM and KRT18." (PMID 40597205, 2025). "Employing a novel algorithm capable of super‐resolution analysis of tumour ecosystems,15we first identified tumour cells based on the expression of EPCAM, TG, KRT18 and KRT19." (PMID 39810624, 2025). "The EMT marker proteins, such as VIM, KRT18, KRT8, and MMP9 are involved in cell structure, motility, and matrix remodeling, which are crucial for tumor invasion and metastasis." (PMID 39858010, 2025). "Tumor clusters c1–c4 exhibited relatively high expression of EPCAM and KRT18, with c4 showing elevated IGF2 expression." (PMID 40098972, 2025).
tumor (continued). "Progression from the first stage of tumor development to the metastatic stage is characterized by a decrease in cells expressing cytokeratin 8 (CK8), cytokeratin 18 (CK18), and the tumor suppressor gene p63." (PMID 40429906, 2025). "We found that the EDEM3 expression in epithelial cells (marked by KRT18, EPCAM, KRT8) was significantly higher in tumour tissues with a large proportion of CAFs (marked by COL1A1, COL1A2, COL6A1, COL6A2) in the GSE188711 CRC dataset." (PMID 39754316, 2025). "The high expression of tumor-related genes (EPCAM, CD24, CDH1, ELF3, KRT18, KRT19, KRT8, and MUC1) in groups 10 and 11 suggests that cells in these groups are tumor cells." (PMID 38693422, 2024). "To substantiate this classification, we examined the expression of hallmark canonical cell markers of cancer epithelial cells (EPCAM, SOX4, KRT7, KRT18, KRT19, KRT8) in C1 (normal epithelial cells) and the other clusters (tumour epithelial cells)." (PMID 38445456, 2024). "CK8 (KRT8), CK18 (KRT18), and EPCAM were expressed differentially (upregulated) in TRG5 tumours, but undetectable in the regressed lesion." (PMID 38630793, 2024). "The peaks of epithelial cells and tumor cells were notably enriched in the gene sets of ‘VIM, KRT5, KRT17’ and ‘KRT8, KRT18, FOXA1’, respectively." (PMID 38581422, 2024). "LINC02253 stabilizes KRT18 mRNA and upregulates KRT18 expression by promoting the recruitment of METTL3 to KRT18 mRNA, activating the MAPK/ERK signaling pathway, and promoting tumor growth and GC cell migration and invasion." (PMID 39678510, 2024). "This analysis was performed using specific marker genes: GPX3 and ALDOB for proximal tubular cells and VIM, KRT18, NDUFA4L2, and NNMT for tumor cells." (PMID 37533434, 2023). "By comparing 2D and 3D cell culture techniques regarding the expression of ANXA1, CD44, KRT18, OCT4, and SOX2OT genes, folding results represented variation in gene expression between tumor cells cultivated in 2D and 3D cultures." (PMID 37884554, 2023). "Consistently, the cytokeratin tumor markers, KRT8, KRT18, and KRT19, were most abundantly expressed in these epithelial cells." (PMID 37430270, 2023). "Both PD-L1-negative and PD-L1-positive patients showed clusters of tumor cells expressing KRT7, KRT8, and KRT18." (PMID 36674951, 2023). "The main cell clusters included T cells (CD3E and CD3D), B cells (CD19), natural killer cells (NCAM1, FCGR3A and KLRD1), myeloid cells (CD86 and CD163) and tumor cells (EPCAM, KRT8 and KRT18)." (PMID 36497182, 2022). "The cells in clusters 3, 4, 6, 7, 10, 15, 23, 25, 26, and 35 originated from tumor specimens and were highly expressed in ALB, KRT18, and CD24; therefore, they were labeled as malignant cells." (PMID 36605219, 2022). "For example, tumor cells showed particularly high expressions of KRT8, KRT18 and TCF7L1, whereas endothelial cells showed particularly high expressions of PECAM1 and VWF.." (PMID 35494058, 2022). "Tumor malignant phenotype related IGFBP2 and KRT18 were significantly enriched in KRAS-Mut subtype, whereas neutrophils and macrophages related CD177, MMP1 and ARG1 were enriched in WT subtypes." (PMID 35836817, 2022). "After quality control, 11,390 tumor cells (TG, EPCAM, KRT18, and KRT19) and 6,808 normal cells (TG, TPO) were obtained for subsequent analysis." (PMID 35359404, 2022). "These tumor cells were positive for Pit‐1, PRL and Syn, with perinuclear punctated structures immunopositive for cytokeratin 18 (CK18)." (PMID 34286902, 2021). "As a result, the ER+ cancer sample was clustered with ER+ tumor cells (ESR1+, KRT18+, and KRT5−), KRT5+/EPCAM+ double-positive cells, cancer-associated fibroblasts (CAFs) (DCN+), macrophages (CD68+), KRT5+/EPCAM− cells, and endothelial cells (VWF+)." (PMID 34685653, 2021). "Soluble protein fragments of keratins, including KRT7, KRT8, KRT18 and KRT19, can be detected in the circulation of cancer patients and are used to monitor disease progression and patient prognostic in certain tumour types." (PMID 34070214, 2021).
tumor (continued). "We also observed a strong cytokeratin 18 staining, and a mild decrease of NANOG signal on IHC staining of ATO/ CDDP combined treated tumor sections." (PMID 32351887, 2020). "Elevated baseline levels of the tumour markers CEA and CA125 (in addition to CA19-9), and total cytokeratin 18 and VEGFR2, as well as CTCs were shown to be prognostic in ABC." (PMID 29925934, 2018). "In this study, we evaluated the association of clinical outcome in 129 CRPC patients with CTCs, tumor-derived Extracellular Vesicles (tdEVs) and plasma levels of total (CK18) and caspase-cleaved cytokeratin 18 (ccCK18)." (PMID 29721202, 2018). "There was the expected corresponding decrease in basal cell markers (KRT5 and TP63) and increase in expression of luminal cytokeratin markers in tumor cells (KRT8 and KRT18)." (PMID 27935821, 2017). "However, the detailed working mechanisms of keratin 18 on tumor metastasis remain unclear." (PMID 25973684, 2015). "Immunohistochemical staining of the tumour revealed that the tumour cells were positive for the epithelial membrane antigen (EMA), cytokeratin 18 (CK18), and vimentin." (PMID 24587922, 2014). "Phenotypes underlying such clustering patterns showed that CTCs maintained higher expression than all tumor cell lines for FOXC1, KRT18, PTEN, NPTN, TGFß1, KRT8, ZEB2, and CXCR4." (PMID 22586443, 2012). "In addition, nuclear fractionation and staining of cleaved (activated) caspase 3 and caspase-cleaved cytokeratin-18 (respectively) indicated that cannibalism led to the apoptosis of the engulfed cells (and occasionally of the cannibals), again similar to our observations in human tumours." (PMID 22821859, 2012). "Immunohistochemically, the tumor cells were positive for the epithelial membrane antigen (EMA), cytokeratin 18 (CK18) and Vimentin." (PMID 20090871, 2009). "Cytokeratin 18 (CK18) is a major component of the intermediate filament of simple epithelial cells and epithelial-derived tumours, and makes up approximately 5% of the total cell protein." (PMID 19603019, 2009). "The morphology of the epithelial compartment was identical to that observed in the same tumor examined immediately after surgery by conventional immunohistochemistry using HEA antibody or cytokeratin 18 (CK18) antibody as epithelial markers." (PMID 16603054, 2006). "We also analyzed the correlation between the expression of CCL2 in tumor cells and macrophage infiltration in GSE125449 cohort and found that there was a positive correlation between the expression of CCL2 in KRT18 + tumor cells and CD68 + macrophages infiltration." (PMID 38970074, 2024). "Thus, EPCAMhigh tumor spots more often demonstrated the expression of such epithelial markers as KRT7, KRT8, and KRT18 compared to EPCAMlow and EPCAM-negative clusters." (PMID 39456890, 2024). "Exceptional responders to therapy exhibit increased RNA abundance of KRT8 and KRT18 relative to nonresponders to therapy, consistent with exceptional responders to therapy having tumours with luminal features." (PMID 38049604, 2023). "First, we categorized clustered data into tumor and stromal populations using a panel of markers for each (epithelial: AQP1, AQP2, EPCAM; endothelial: PLVAP, CD31, CD34; fibroblast: PDGFRα, PDGFRβ; immune: CD45; tumor cell: CXCR4, VIM, KRT18, PAX8, PAX2, CA9, CD10)." (PMID 34884982, 2021). "Furthermore, we analyzed the expression of two cell type specific genes, the epithelial marker keratin 18 (KRT18) and the leukocyte specific marker gene CD45 (PTPRC), to differentiate between tumor epithelial cells and WBCs." (PMID 34440208, 2021). "In addition, KRTs and notably KRT7, KRT18 and KRT19, are widely used to detect circulating tumor cells in the blood or detached tumor cells in ascites." (PMID 34070214, 2021). "The frequency of Krt18+ tumor cells did not decrease on CYH33 treatment in both Balb/c and nude mice." (PMID 34373258, 2021).
tumor (continued). "Interestingly, cytokeratin 18, a marker expressed in the ependymal layer and in our LATS1/2 cKO tumours was among the top 10 increased genes in nlsYAP5SA mice." (PMID 32404936, 2020). "The tumour was found to be positive for cytokeratin 18 (CK18) and was negative for Arg-1, hepatocyte, glypican-3 (GPC-3), and CK7 in IHC analysis." (PMID 31064408, 2019). "Tumor sizes of 17-20-months-old wt, Krt18+/− and Krt18−/− mice did not significantly differ between the genotypes." (PMID 27689336, 2016). "In immunohistochemistry, the majority of Krt18−/− tumor cells were, as expected, keratin-negative whereas Krt18+/− tumor cells were keratin-positive with considerable variation in staining intensity suggestive of variations in IF content and density." (PMID 27689336, 2016). "Immunohistochemical analysis shows that tumor sections from the WIF1 transfected PC3 cell line exhibited a marked increase in E-cadherin and Keratin-18 while tumor sections from vector control cell line revealed no or very weak staining." (PMID 20573255, 2010). "Pancytokeratin (Pan-CK), cytokeratin 7 (CK7), cytokeratin 18 (CK18), olfactory marker protein (OMP) and Kiel 67 were examined in ENA tumours to clarify the immunohistochemical characteristics of ENA, analyse the tumour origin and screen for suitable antibodies for ENA tumour cell identification." (PMID 40144068, 2025). "Epithelial makers (KRT18, KRT19, KRT17, KRT7, and CLDN4) were also highly expressed, indicating that M2 may be derived from transdifferentiation of epithelial cells in the tumor." (PMID 35265520, 2022). "The samples were grouped based on their KRT18 expression level regardless of tumor type." (PMID 34290732, 2021). "Krt18 expression was not different between any tumor groups." (PMID 25472762, 2014). "M65 Elisa, which quantitates different forms of circulating cytokeratin 18 (CK18) as putative surrogate markers of both apoptotic and nonapoptotic tumour cell death, was shown to be highly reproducible: calibration curve linearity r2=0.996, mean accuracy >91% and mean precision <3%, n=27." (PMID 16804528, 2006). "Notably, we found that the ductal cell markers and epithelial cell-specific markers reported previously, such as EPCAM, KRT18, SOX9, KRT19, MUC1, and FXYD3, were commonly expressed in the majority of clusters except for cluster 17, confirming tumor cell identity." (PMID 37324492, 2023). "In addition, six genes, KRT18, ARPC5L, ACTG1, ARPC2, EZR, and YWHAZ, were simultaneously enriched in tumors and tumor tissues highly expressing TNFRSF11B, which may enhance pathogenic E. coli focal adhesion, actin filament binding, and cadherin binding, as demonstrated by GO functional analysis." (PMID 34938284, 2021). "Interestingly, FC2 displayed the highest correlation with epithelial cells and showed specific expression of tumor epithelial markers KRT8, KRT10, and KRT18, as well as the EMT markers SNAI1 and SNAI2, suggesting that FC2 may have the tumor‐like aggressive potential." (PMID 34459128, 2021). "Indeed in some cases of Krt18+/− and Krt18−/− livers amplifications and deletions were observed in non-neoplastically transformed liver tissue also at 12 months of age, i.e., before the onset of tumor occurrence but not in wt mice." (PMID 27689336, 2016). "Immunohistochemical staining revealed that the tumor was positive for alpha-smooth muscle actin, but negative for CD34, desmin, keratin 18, S-100 protein, melan A, c-kit, and STAT6." (PMID 38805072, 2024). "Immunohistochemically, the tumor was positive for alpha-smooth muscle actin, but negative for CD34, desmin, keratin 18, S-100 protein, melan A, c-kit, and STAT6." (PMID 38805072, 2024). "Compared with tumor cells at the primary site, metastatic tumor cells still retained high expressions of KRT8 and KRT18, whereas metastatic tumor cells no longer expressed MMRN1, PROX1, TCF7L1, SCG3 and SV2C." (PMID 35494058, 2022).